MIR383 (microRNA 383)
Synonyms: hsa-mir-383; MIRN383; mir-383
Gene: MicroRNA gene on chromosome 8 (14,853,438 to 14,853,510, reverse strand). Ensembl gene ENSG00000199127.
Gene Ontology:
Biological process: miRNA-mediated post-transcriptional gene silencing
Cellular component: RISC complex
Homologues: Orthologues: chimpanzee ptr-mir-383 (100% identical), macaque MIR383 (100% identical), pig ssc-mir-383 (99% identical), rat Mir383 (97% identical), tropical clawed frog xtr-mir-383 (95% identical), guinea pig MIR383 (93% identical), rabbit MIR383 (82% identical).